CCL5 (C-C motif chemokine ligand 5)
Diseases named in the same sentence as CCL5 in open-access papers (continued):
Sharing a sentence is not in itself a finding about the gene and the disease.
breast cancer (continued). "CCR1, 3 and 5 are known as the receptors of CCL5, and we then evaluated them in breast carcinoma tissues and examined the association between CCL5 immunoreactivity in stromal cells and clinicopathological factors according to the status of CCR1, 3 and 5 in carcinoma cells." (PMID 33671956, 2021). "MSCs transfected with only a CCL5 promoter‐driven or ganciclovir‐induced suicide gene can also cause a degree of tumour cytotoxicity in animal models and clinical trials of hepatocellular carcinoma, pancreatic cancer, and breast cancer." (PMID 32588948, 2020). "Further, we used the KM plotter platform (including a higher number of samples, i.e., the ones for which gene expression array were available either from TCGA or deposited in GEO) to evaluate an association between CCL5 expression and breast cancer and TNBC patients' survival." (PMID 31921621, 2019). "In addition, a significant association was found between breast cancer and the CCL5 rs2280789-G/G homozygous genotype (OR = 5.52, P = 0.019)." (PMID 31921621, 2019). "Furthermore, post-treatment chemokine (C-C motif) ligand 5 (CCL5) increase has been associated with responsiveness to immunotherapy (Imiquimod) in breast cancer skin metastasis." (PMID 31921621, 2019). "While the effects of CCL5 on malignancy may be strongly implicated in multiple myeloma and breast cancer, in which CCL5 promotes both proliferation and migration, their contribution in HT29 and DLD-1 cells seems to mainly affect their motility." (PMID 29872080, 2018). "We therefore hypothesized that CCL5 played a key role in the interaction between breast cancer cells and TAMs and CCL5 might be associate with cancer EMT and aerobic glycolysis." (PMID 29299159, 2017). "Moreover, breast cancer-mediated production of the chemokine CCL5 (RANTES) by neighboring tumor-associated mesenchymal stroma/stem cells can act in a paracrine manner on the cancer cells to promote their motility, invasion, and metastasis." (PMID 28785589, 2017). "Viewed altogether, the data indicate that the effects of CCL5 treatment on the different breast cancer cell types are associated with enhanced metabolic activity that would support the energy and biosynthetic demands of tumour cell proliferation, migration and invasion." (PMID 27335323, 2016). "CCL5 expression is strongly associated with the progression of breast cancer, particularly the triple-negative breast cancer (TNBC), and may represent an immunotherapeutic target in the TNBC." (PMID 24523569, 2014). "This was associated with enhanced production of chemokines (CCL5, CXCL10, CXCL11, IL-15) and increased CD8+ T cell infiltration, causing Granzyme B-mediated induction of breast cancer cell apoptosis." (PMID 40940894, 2025). "Elevated levels of CCL5/RANTES have been observed in specific malignant neoplasms, including breast cancer, malignant melanoma, and prostate cancer." (PMID 40076479, 2025). "CCL2 and CCL5 are among the most extensively studied chemokines in the breast cancer microenvironment." (PMID 40909271, 2025). "The FBXO24-mediated depletion of LSD1 led to increased expression of CCL5 and CXCL10 in breast cancer cells, which was associated with increased level of H3K4me2 in the promoter regions of their genes." (PMID 40940894, 2025). "High CCL5 expression has a role in breast cancer cell resistance to trastuzumab by ERK phosphorylation and tamoxifen by STAT3 activation." (PMID 40076892, 2025). "Up-regulation of C-C motif chemokine ligand 5 (CCL5) is a critical signature in the genesis and progression of breast cancer." (PMID 40725945, 2025). "In mammary tumors, Ccl2, Ccl3 and Ccl5 were shown to modulate the infiltration of monocytes, resulting in the accumulation and activation of tumor-associated macrophages, TAMs." (PMID 39566333, 2025).
breast cancer (continued). "Böttcher and colleagues analyzed The Cancer Genome Atlas data and found that a cDC1 signature was positively correlated with an XCL1/XCL2 and CCL5 chemokine signature and an NK-cell signature in breast cancer, melanoma, and lung adenocarcinoma." (PMID 39777457, 2025). "CCL5 attracts Tregs and mesenchymal stem cells, fostering immune suppression and stromal remodeling, especially in basal-like breast cancers." (PMID 41007766, 2025). "For example, HSF1 impairs immune responses in breast cancer by inhibiting CCL5-mediated CD8 + T cell infiltration, and CCL5 is recognized as a promising biomarker to guide immunotherapy in ovarian cancer." (PMID 41444923, 2025). "Because we previously reported that CXCL5, CCL2, CCL3, and CCL5 occur at low levels in CM collected from aggressive breast cancer cell lines, here we focused on other abundantly secreted chemokines." (PMID 40833805, 2025). "A similar observation was reported for patients with primary breast cancer, where Treg cells and CCL5 were co-expressed with standard prognostic markers for breast cancer." (PMID 38318526, 2024). "Conversely, stimulated NK cells can produce T-cell-recruiting chemokines, including CCL2 and CCL5, in breast cancer patients." (PMID 38928033, 2024). "As early as 2007, studies confirmed that contact between MSCs and breast cancer cells (BCCs) in the breast cancer environment increased the secretion of CCL5 and SDF-1α and the metastatic potential of cancer cells." (PMID 37588208, 2024). "CCL5 promotes aerobic glycolysis in breast cancer cells by modulating AMP-activated protein kinase (AMPK) signaling, further inducing EMT and migration." (PMID 39430253, 2024). "Breast cancer cells can stimulate the de novo secretion of CCL5 from mesenchymal stem cells within the tumor stroma, which then acts in a paracrine fashion on cancer cells to enhance their motility, invasion, and metastasis." (PMID 38928033, 2024). "TNF-α stimulates the stromal cells and releases elevated levels of CCL2, CXCL8, and CCL5, which have tumor-promoting solid activities in general and breast cancer, mainly when derived from stroma cells." (PMID 38541912, 2024). "CCL5 secreted by TAMs activates AMPK signaling in breast cancer cells, promoting aerobic glycolysis, thereby inducing EMT and migration." (PMID 39430253, 2024). "We found that DSF/Cu up-regulated the expression of CXCL10, CCL5 and IFN-β in multiple high metastatic breast cancer cell lines, which was associated with the activation of the STING-TBK1-IRF3 pathway." (PMID 38370371, 2024). "NF-κB activity in breast cancer mouse cells can induce the expression of CCL5, which drives the recruitment of CCR5-expressing macrophages, which supplies breast tumor cells with collagen that promotes their proliferation." (PMID 38928033, 2024). "Studies have shown that breast cancer cells increase MSC production of chemokine (C-C motif) ligand 5 (CCL-5), which regulates tumour invasion." (PMID 39135088, 2024). "This quantitative imaging approach demonstrated that the CCL5/collagen IV ratio has a significant prognostic value for disease-free survival in patients with breast cancer, providing valuable information for tailoring patient-specific therapeutic strategies." (PMID 38730959, 2024). "Trastuzumab-induced NK cell activation against SKBR3, BT474 and HC1954 HER2-positive breast cancer cells resulted in the secretion of CCL5, IFN-γ and the consequent production of CXCL9 and CXCL10, as analysed by ELISA in cell-free coculture supernatants." (PMID 38167224, 2024). "More specifically, after silencing the CLOCK gene, the genes primarily involved in breast cancer progression included CCL5, SP100, and BDKRB2." (PMID 39587706, 2024). "We have identified that the underlying biology of the DDIR signalling in GOA, similar to breast cancer, is associated with constitutive gene up-regulation of the chemokines CXCL10 and CCL5 and an inflamed TME." (PMID 38744099, 2024).
breast cancer (continued). "CCR1 is the C-C motif chemokine receptor ligand 5 (CCL5) and has been reported to be a chemokine that fosters metastasis and is expressed during crosstalk between breast cancer and stromal cells." (PMID 38920683, 2024). "Tregs are immunosuppressive and Treg cell recruitment has been shown to depend on CCL5 in tumors including breast cancer." (PMID 37759462, 2023). "In an inducible mammary-epithelial-cell targeted Her2 model of breast cancer, a tumor microenvironment inflammatory program driven by TNFα/NFκB signaling promoted immune cell infiltration via CCL5." (PMID 37759462, 2023). "Breast cancer patients with high CCL5 expression had worse disease-free survival and breast cancer-specific survival." (PMID 37759462, 2023). "Other studies have reported CCR5 as the main receptor for CCL5 in the interaction between breast cancer cells and stromal cells; however, these studies have exclusively been conducted using 2D culture models and BMSCs." (PMID 37444610, 2023). "In research on residual breast cancer cells, Her2 downregulation‐driven CCL5 has been reported to promote breast cancer recurrence via macrophage recruitment." (PMID 38045829, 2023). "CCL5 expression has been reported to be stimulated by the interaction of ASCs and breast cancer cells." (PMID 37444610, 2023). "Although initially characterized in immune cells, CCR5 signaling in MDA-MB-231 breast cancer cells showed CCL5 and serum-induced calcium signaling." (PMID 37759462, 2023). "Further studies are needed to evaluate the efficacy of anti‐CCL5 neutralizing antibody in different molecular subtypes and clinical stages of breast cancer." (PMID 36794651, 2023). "CCL5 expression has also been correlated with breast cancer poor prognosis, lymph node metastasis, residual tumor size, and tumor infiltration of lymphocytes after neoadjuvant chemotherapy." (PMID 37759462, 2023). "The CCL5-induced infiltration of cytotoxic T cells into tumors turned “cold” colon and breast cancers into “hot” ones." (PMID 39872623, 2023). "Melanoma cell behavior was influenced by TGF-β, and the invasive capacity of breast cancer cells was modified by MSC-secreted CCL5 and CCL9 and the activation of MMP as well as by the induction of EMT via activated ERK signaling." (PMID 37781195, 2023). "The CCL5-mediated induction of cellular invasion was observed in diverse breast cancer cell types (MDA-MB-231, Hs587T, SUM-159, MCF-7, MCF10A-NeuT, MCF10A-Ras, and MCF10A-Src)." (PMID 37759462, 2023). "There is a known inverse correlation between RKIP and CCL5 in breast cancer datasets, in addition to there being direct correlations between loss of RKIP and poor prognosis, and heightened CCL5 expression and poor prognosis." (PMID 36765912, 2023). "As we observed a highly elevated CCL5 secretion in our 3D ASC/breast cancer model, we wanted to pursue this further and characterize the expression of the corresponding receptors." (PMID 37444610, 2023). "Breast cancer cells promote the synthesis of CCL5 (also called RANTES) from MSCs by communicating with C-C chemokine receptor type 5, enhancing cancer cell motility, invasion, and distant spread in vitro and in vivo." (PMID 37849741, 2023). "It was shown that the knocking down of HMGA2 by specific siRNAs significantly decreased CCL5 transcripts in cultured breast cancer cells." (PMID 36765912, 2023). "Elevated levels of CCL5 in tissues or plasma predicts poor outcomes in breast cancer, cervical cancer, prostate cancer, ovarian cancer, gastric cancer, and pancreatic cancer." (PMID 37759462, 2023). "A recent study found that cancer cell-derived lactate promoted breast cancer cells to secrete chemokine C–C Motif Chemokine Ligand 5 (CCL5) through the Notch signaling pathway, which polarized the M2 phenotype of chemotactic macrophages." (PMID 36709284, 2023).
breast cancer (continued). "Cancer-cell-derived-lactate increased the secretion of CCL5 through Notch signaling in tumor-associated macrophages, and CCL5 in turn induced EMT and aerobic glycolysis in breast cancer cells." (PMID 37759462, 2023). "CCL5 promoted breast cancer recurrence through recruitment of macrophages into the residual tumors, and a high TAM number has been associated with poor prognosis in breast cancer." (PMID 37759462, 2023). "In HER2+ murine breast cancer, after tumor regression, CCL5 remained elevated in the residual tumor, recruiting Tumor-Associated Macrophages (TAMs) that promoted tumor recurrence." (PMID 37759462, 2023). "Studies have shown that CCL5 promotes tumor cell growth and inhibits paracrine and autocrine apoptosis of breast cancer." (PMID 36816977, 2023). "The requirement for normal NF-kB and IRF signaling for the observed heightened CCL5 expression in breast cancer tumors has been confirmed." (PMID 36765912, 2023). "Over 95% of TNBC tumors expressed CCR5; therefore, increased CCR5 expression and elevated CCL5 levels predict a poor prognosis of breast cancer." (PMID 37759462, 2023). "As a proof-of-concept, the adipocyte/breast cancer spheroid model was used to analyze the expression of CCL5 and CCR1 complementary to the ASC co-spheroid model." (PMID 37444610, 2023). "Among them, CCL5 has been directly shown to promote breast cancer by monocyte recruitment to the TME." (PMID 36765912, 2023). "The chemokine CCL5 produced by MSCs combines with the homologous receptor CCR5 on human breast cancer cells (BCC) can promote lung metastasis of breast cancer." (PMID 37666813, 2023). "Cell invasion and migration experiments suggested that CCL5 essentially restrained the metastasis of breast cancer." (PMID 36090993, 2022). "In vivo studies demonstrate that breast cancer cells stimulate MSCs to resecrete CCL5, which then acts in a paracrine manner on tumor cells." (PMID 35702353, 2022). "There is a wealth of evidence showing that CCL5 is co-opted in breast cancer and in many other types of tumors, such as pancreatic, ovarian, prostate and glioma cancer." (PMID 36430633, 2022). "In this study, CCL5 in serum was related to the PR and clinical stage of breast cancer patients, and CCL5 in tumor tissue was related to ER, PR, nuclear grade, clinical stage and molecular subtyping." (PMID 36033472, 2022). "The results showed that CCL5 levels in serum were higher in PR-negative breast cancer (P = 0.035) and higher in breast cancer patients with late clinical stage disease (P < 0.001)." (PMID 36033472, 2022). "CAIX promoted the production of known soluble mediators of breast cancer metastasis, CXCL10, CCL5, and G-CSF, by hypoxic breast cancer cells." (PMID 35719975, 2022). "CCL5 is a potent chemokine with a physiological role of immune cell attraction and has gained particular attention in R&D for breast cancer treatment." (PMID 36430633, 2022). "Except CXCL10, high expression levels of CCL5, CCL19 and CXCL9 were significantly associated with better prognosis in breast cancer patients." (PMID 35359417, 2022). "In vitro and in vivo tests show that blocking or knocking down CCL5/CCR5 is detrimental to tumors such breast cancer and limits metastases." (PMID 36430633, 2022). "CCL5 is highly expressed in the serum of breast cancer and the patients with high expression of CCL5 were more likely to have lymph node metastasis." (PMID 35083488, 2022). "In a mouse model of Her2-driven breast cancer, CCL5 over-expression promoted tumor recurrence by recruiting CCR5-expressing macrophages." (PMID 33603130, 2022). "Breast cancer cells that secrete CCL5 act on mononuclear macrophages towards TAMs which can promote tumor migration and invasion." (PMID 34914196, 2022). "Recent studies have also confirmed that CCL5/CCR5 can affect the polarization of M2 macrophages through the MEK/STAT3 signaling pathway in luminal B breast cancer." (PMID 36033472, 2022).
breast cancer (continued). "Taken together, these data illustrate that the lncSNHG5-ZNF281-CCL2/CCL5 signaling axis in CAFs plays an important role in breast cancer metastasis in vivo." (PMID 36438499, 2022). "A large source of CCL5 in breast cancer is a juxtracrine relationship between adipose-derived stem cells and breast cancer cells." (PMID 36430633, 2022). "CCL5 affects the biological behavior of breast cancer and the prognosis of breast cancer patients through the CCR5/Treg signaling pathway, which is likely to be a potential therapeutic target for breast cancer." (PMID 36033472, 2022). "CCL5 abnormal expression is found in astrocytoma, breast cancer, hepatocellular carcinoma and mutiple other cancers." (PMID 36514094, 2022). "CCL5 expression by immune cells was reported to be a contributor to the EMT process of locally advanced breast cancer." (PMID 36148946, 2022). "Kaplan–Meier analysis was used to analyze the effect of CCL5 on the prognosis of breast cancer patients." (PMID 36033472, 2022). "Enrichment analysis was used to study the possible pathway by which CCL5 affects breast cancer progression." (PMID 36033472, 2022). "CCL2 and CCL5 have also retained attention in breast cancer, as they are expressed by cancer cells and promote the recruitment of TAMs and metastasis by inducing Th2 polarization of CD4+ T cells." (PMID 36588678, 2022). "CCL5 play a key role in translating the metabolic communication between TAMs and breast cancers, increasing aerobic glycolysis, migration and invasiveness of the cancer cells." (PMID 34914196, 2022). "Multiple studies indicated that circulating CCL5 promotes breast cancer metastasis, so this connection warrants further study." (PMID 35727842, 2022). "CCL5 has been reported to help the progression of breast cancer, so in this study, CCL5−/− was used to explore the role of host-derived CCL5 after cryo–thermal therapy." (PMID 35327361, 2022). "These researchers also found that lung metastasis and colonization of tumor cells increased after mice were given both breast cancer cells and MSCs, suggesting that CCL5 facilitates the metastatic ability of tumor cells." (PMID 35702353, 2022). "CCL5 is secreted by the mesenchymal stem cells in breast cancer cells, which then enhances their motility, invasion, and migration." (PMID 35159385, 2022). "We next confirmed that miR-155 overexpression upregulated Ccl5 and Cxcl9/10/11 expression in murine breast cancer cell lines using qPCR." (PMID 35925680, 2022). "This study aimed to reveal the mechanism of CCL5 in the invasion, metastasis, and prognosis of breast cancer." (PMID 36033472, 2022). "In line with our observations in WB1P and WB1P-Myc mammary tumors, expression of CCL5 and pSTAT1 was induced upon BRCA1/2 depletion, and was suppressed in MYC-overexpressing BT-549 cells." (PMID 36323660, 2022). "CDK4/6 inhibitor promoted the recruitment of tumor-infiltrating lymphocytes by inducing CCL5 secretion in melanoma and in breast cancer." (PMID 37181790, 2022). "A reduction in CCL5 at all Clic4 KO timepoints is particularly notable since CCL5 is reported to influence the development of breast cancer metastasis in human patients and experimental models." (PMID 35727842, 2022). "CCL5 is also ubiquitous across breast cancer cases, being present at stages I, II and III, and over 95% of triple-negative breast tumors are CCR5+." (PMID 36430633, 2022). "The CCL5–CCR5 pathway is one of the most important chemoattractant signal axes in BCa and increased CCL5 expression in tumor tissue is largely correlated with an advanced stage of breast cancer." (PMID 35359417, 2022). "PAI-1 induces the production of CCL5 in endothelial cells, creating a positive feedback mechanism that causes the dissemination and production of more PAI-1 breast cancer cells." (PMID 35053485, 2022).